PML (PML nuclear body scaffold)
Diseases named in the same sentence as PML in open-access papers (continued):
Sharing a sentence is not in itself a finding about the gene and the disease.
infection (continued). "The involvement of PML-NBs in sensing and silencing incoming viralgenomes is likely a general mechanism that could control the infection by many viruses,whose infectious cycle occurs entirely or partly in the nucleus." (PMID 28357326, 2016). "The stable recruitment of constituent PML-NB antiviral factors correlates well with a cooperative restriction in viral gene expression, a process that can limit the onset of productive infection and lead to the establishment of viral quiescence." (PMID 27099310, 2016). "Thus, Cas9/gRNA 2A exerts its antiviral activity by inhibiting expression of multiple HSV-1 genes whose products are required for the infection cycle and halting of host-derived anti-viral events including the assembly of PML bodies." (PMID 27064617, 2016). "It is unclear at the moment how this relocalization works and why it takes place in only 50% of the infected cells, but, interestingly, the relocalization of PML to the cytoplasm of infected cells early during infection correlates with the early effect of PML on HIV reverse transcription." (PMID 26703718, 2015). "In addition, we found that the knockdown of PML already enhances retroviral reverse transcription, indicating that the PML-mediated block to infection already occurs early during the viral life cycle." (PMID 26703718, 2015). "Notably, low expression levels of viral proteins were detected in PML-knockdown cells, even at late times of infection (e.g., 12 hpi and 18 hpi), in contrast to the expected levels detected in infected Vero-shRNA-GAPDH cells." (PMID 26389938, 2015). "Since we found that the knockdown of PML enhanced HIV-GFP infection in HFFs, we next asked whether the overexpression of PML would be able to reduce infectivity in these cells." (PMID 26703718, 2015). "First, PML-NBs form part of an intrinsic antiviral response through their ability to silence gene expression from certain DNA virus genomes, such as members of the Herpesviridae family, upon infection." (PMID 25848798, 2015). "To test this hypothesis, we determined the sub-nuclear localization of LANA and the ND10 core component PML during the early stages of a de novo infection by confocal immunofluorescence (IF) microscopy." (PMID 25033267, 2014). "We constructed a recombinant HCMV expressing hIE1 lacking the C-terminal IE1IDR and could observe that this virus exhibited a severe defect to disperse PML after infection of HFFs." (PMID 25412268, 2014). "Further analysis and functional annotation of all up- and downregulated host genes strongly suggest that the transient increase in Sp100 and PML transcription is due to a pronounced but transient interferon response that is largely ablated at approximately 48 h post infection." (PMID 25033267, 2014). "It will thus be interesting to study whether Spindlin1 also localizes to PML bodies in cells in normal condition or during infection." (PMID 25211330, 2014). "In addition to its effects on the innate immune system, IE1 is required to overcome the PML-NB-mediated intrinsic immunity that targets HCMV immediately upon infection." (PMID 25412268, 2014). "Although the functions of PML-NBs in herpesvirus replication remain elusive, multiple herpesviruses have evolved ways to disassemble or disperse PML-NBs at the early phase of lytic infection." (PMID 23990779, 2013). "Because PML-NBs act as general sensors of genomic damage, regulates cellular senescence and are thought to participate in SAHF formation, we investigated whether PML-NBs could be affected following infection by pks+ E. coli." (PMID 24116215, 2013). "In addition, studies performed with all PML isoforms demonstrate that only PMLIV protects cells from infection with rabies virus, VZV, or EMCV." (PMID 23734343, 2013). "Disassembly of PML bodies early after infection is a common characteristic of herpesviruses." (PMID 23990779, 2013).
infection (continued). "More broadly, our study elucidates the importance of PML NBs for the innate control of a viral pathogen during infection of differentiated cells within their tissue microenvironment in vivo and the requirement for a viral protein with SUMO-binding capacity to counteract this intrinsic barrier." (PMID 21901090, 2011). "Thus, PML cages conferred antiviral activity at a later stage of infection by a mechanism completely different from PML suppression of early viral gene transcription." (PMID 21304940, 2011). "PML cages were also more prominent later in infection, at the stage of viral capsid assembly." (PMID 21304940, 2011). "In uninfected PML depleted cells these two ND10 proteins are dispersed and do not form any co-localising foci, so their aggregation in association with IE2 foci during infection is entirely consistent with recruitment into novel foci." (PMID 22355446, 2011). "HHV-5 genomes also co-localize with PML-NBs shortly after infection." (PMID 20838604, 2010). "Nonetheless, it seems likely that counteracting intrinsic repression mediated by ND10 or at least one of its components (i.e., PML) is a key activity by which CMV IE1 facilitates productive viral replication at low viral input multiplicities (assumed to be the natural mode of infection)." (PMID 21994568, 2009). "ICP0 initially precisely colocalizes with ND10 at early times upon infection and subsequently mediates the disaggregation of PML-NBs by inducing the degradation of the SUMO-1 modified forms of PML and Sp100, leading to the release and dispersal of other ND10 proteins." (PMID 21994592, 2009). "For tegument proteins or those expressed early in infection, the disruption of PML NBs may directly contribute to viral infection." (PMID 18617993, 2008). "An infection block between genome circularization and viral gene expression suggested that PML bodies (ND10 domains) might be involved in the ORF75c− phenotype." (PMID 18648660, 2008). "However, all three herpesviruses that we tested clearly have multiple mechanisms by which they can disrupt PML NBs, likely reflecting the importance of this phenomenon and of PML-related pathways for successful infection." (PMID 18617993, 2008). "To investigate whether the colocalization of histone H3.3 at vDNA correlated with its constitutive localization at PML-NBs prior to nuclear infection and deposition on viral genomes, we screened a panel of cell lines for endogenous histone H3.3 colocalization at PML-NBs." (PMID 40834051, 2025). "Indeed, this hypothesis was proven to be correct in a recent study: HSV-1 genomes were shown to colocalize with PML-NB during a latent infection only in the presence of type I IFN before the start of infection in an in vitro latency model." (PMID 38140525, 2023). "However, JEV can manipulate the PML-mediated innate immune response after infection." (PMID 38031162, 2023). "However, HPV requires PML protein for efficient establishment of infection." (PMID 36016419, 2022). "Having observed that PML cages arise in close proximity to viral replication centers, it was tempting to speculate that these structures exert an additional antiviral activity during the late phase of infection." (PMID 35319461, 2022). "Although the downstream epigenetic changes to the HSV genomes that are associated with PML-NBs in neurons is not known, this indicates that exposure to different cytokines during initial infection can regulate the nature of latent infection and later ability to reactivate." (PMID 35772067, 2022). "Finally, we examined whether the PML-NBs that have encased input viral genomes develop into PML cages at late times after infection." (PMID 35319461, 2022). "Notably, the number of PML NBs increases during infection with Shigella." (PMID 34513832, 2021).
infection (continued). "However, a rechallenge of previously infected Ccr2-/- mice revealed increased bacterial killing (as indicated by a reduction in S. aureus CFU), decreased infiltrating PML, and less skin IL-1β concentrations as compared to naïve counterparts 5 days after (re-)infection." (PMID 32639232, 2020). "The viral transactivator pp71 is excluded from the nucleus of non-permissive cells, and since pp71 has been shown to be important for antagonising the functions of PML bodies during lytic infection, exclusion of pp71 may help mediate PML-mediated repression of the MIEP." (PMID 30761409, 2019). "Consequently, many DNA viruses, such as herpes simplex 1 (HSV-1), human cytomegalovirus (HCMV), simian virus 40 (SV40) and adenovirus 5 (ADV5), target PML NBs during primary infection and induce the reorganization and degradation of the residing proteins, including PML protein and Sp100." (PMID 30802273, 2019). "In addition, PML-NB size is increased in both infected cells and cells that express P3, an N-terminal truncated version of the phosphoprotein P. The P3 is believed to mediate the enlargement of PML-NBs during infection." (PMID 29922292, 2018). "PML and Cajal Bodies may form adjacent to each other, and can vary in number and location between different cell lines, different species, different organs, and as a result of infection or transformation." (PMID 30041613, 2018). "Interestingly, BKPyV DNA foci were found adjacent to PML-NBs during late infection and it has been suggested that the reorganization of PML-NBs could be a strategy used by BKPyV to inactivate their intrinsic antiviral functions." (PMID 29099746, 2017). "In contrast, viruses like KSHV, for which the default outcome of infection in most if not all cells is latency, encode for vFGARATs that are not capable of degrading PML but affect other components of ND10-NBs like SP100, DAXX or ATRX, and often in a more subtle way than plain degradation." (PMID 29065450, 2017). "Even if incoming Ad genomes may not associate with PML-NBs upon infection, modulation of the bodies and inhibitory roles of its components during Ad infection is well established, in common with herpesviruses." (PMID 27782081, 2016). "PML-associated nuclear bodies punctate structures were evident by fluorescent microscopy in the nuclei of HSV-1-uninfected L7 cells expressing only Cas9, but infection of these cells with HSV-1/GFP completely changed the structure of PML punctate structures coincident with HSV-1 localization." (PMID 27064617, 2016). "HCMV IE2 could be another example for a viral protein, which on one hand is able to independently target PML-NBs, while on the other hand it was shown to co-localize with viral genomes at the bodies in the infection context, potentially linking the genome to PML-NBs." (PMID 27782081, 2016). "Indeed, some DNA viruses (e.g., Papillomaviruses and Polyomaviruses) localize their replication centres within or at the periphery of PML-NBs to accomplish their infection cycle, while Herpesviruses have been found to block PML-NBs antiviral responses by the mislocation of these domains." (PMID 26389938, 2015). "Thus, to determine whether PML affects infection in HIV target cell types, we analyzed HIV infectivity in T cell lines and myeloid cells in the absence or presence of PML." (PMID 26703718, 2015). "Additionally, PML-NBs showed a tendency to become juxtaposed to the activated DNA damage response (DDR) factors foci and further investigation disclosed a proviral role for PML protein in ASFV infection, since viral progeny was decreased in PML-knockdown cells." (PMID 26389938, 2015). "NB dispersal correlates with the functional activities of IE1 during infection and a PML knock-down efficiently compensates for IE1 in promoting replication of an IE1-deficient virus, establishing IE1 as an important antagonist of PML-mediated cellular repression of viral replication." (PMID 25412268, 2014).
infection (continued). "Whether the association between DNA virus genomes and PML NBs has a positive or negative influence on the outcome of infection has long been debated." (PMID 23825941, 2013). "Thus, the inhibition of PML-NBs formation in early infection might be necessary to allow the viral replication/transcription to proceed efficiently in vivo." (PMID 23990779, 2013). "The HSV-1 immediate-early protein ICP0, a viral ubiquitin E3 ligase, degrades both PML and SP100 during infection, which facilitates efficient HSV-1 replication." (PMID 39823515, 2025). "Then, as viral replication and innate immune signaling proceed during infection with ICP0 RF, by 8 hpi, the interaction profile of SLFN5 remains correlated with IFI16, while those of PML, DAXX, and SP100 diverge to cluster with one another." (PMID 40577456, 2025). "At 4 h post-infection, α3 colocalized with immediate early 1 (IE1) and the promyelocytic leukemia protein (PML)." (PMID 40143325, 2025). "During infection, HSV-1 significantly interacts with and remodels specific nuclear structures (e.g., PML NBs, centromeres, and telomeres)." (PMID 38932138, 2024). "Importantly, our imaging analysis could readily identify changes in host factor recruitment and spatial proximity at vDNA under a variety of genetic (e.g., NTC vs. PML or Daxx KO) and infection (WT vs. ΔICP0 HSV-1) conditions, demonstrating the sensitivity of the approach employed." (PMID 39185184, 2024). "Upon infection of PK15 cells with JEV, a significant reduction in the number of PML-NBs was observed." (PMID 37928180, 2023). "In the early stage of infection, HCMV IE1 inhibits PML de novo SUMOylation and degrades Sp100 to initiate viral transcription." (PMID 37058447, 2023). "There is precedent for examining DNA and PML in a single-cell microscopic analysis of HPV infection, which showed great heterogeneity in infection kinetics among individual cells." (PMID 37154756, 2023). "By correlative light and electron microscopy (TEM and FIB-SEM tomography), we identify PML cages as circular clusters of viral capsids that are enveloped by PML fibers and occur after high MOI infection with HCMVΔIE1, but not wild-type HCMV." (PMID 35319461, 2022). "During the latent and reactivation phase of MDV infection (7–28 dpi), the transcriptional upregulation of chicken IL-1β, IL6, IL-8L1, IFN-γ, and PML in the spleen and bursa induced by MDV/RB1B infection was overall stronger than that of MDV/CVI988." (PMID 36680047, 2022). "The tegument-delivered protein pp71 is imported into the nucleus immediately upon infection, where it leads to the displacement of ATRX from PML-NBs, followed by proteasomal degradation of Daxx." (PMID 36233232, 2022). "Immediately upon infection, the majority of HSV-1 DNA is surrounded by PML protein; however, when ICP0 is expressed, PML is rapidly eliminated, and viral DNA is once again entrapped by SLFN5 protein." (PMID 35216035, 2022). "Upon infection, SUMO 2 was re-localized either to structures resembling viral E4orf3/PML tracks or viral RCs." (PMID 35336871, 2022). "At different times after infection, cells were fixed for antibody staining to detect IE2 and/or PML in combination with click chemistry to visualize HCMV input genomes (vDNA)." (PMID 35319461, 2022). "The results of our investigation showed that the transcription levels of PML in the spleen were upregulated at 7 and 14 dpi after MDV/RB1B infection, but for CVI988 infection, they were only upregulated at 7 dpi." (PMID 36680047, 2022). "Upon infection, the tegument-delivered protein pp71 is imported into the nucleus where it leads to dissociation of ATRX from PML-NBs, followed by proteasomal degradation of Daxx." (PMID 35319461, 2022). "As a viral countermeasure, EV71 has evolved to significantly reduce the number of PML NBs and PML-III/-IV protein levels early upon infection, which further reduced as infection progressed." (PMID 33807177, 2021).
infection (continued). "PML−/− MEFs and PML−/− mice displayed higher sensitivity to VSV replication and infection compared to their WT counterparts." (PMID 33807177, 2021). "During lytic infection, HCMV expresses two regulatory proteins that act in a sequential manner to efficiently antagonize PML-NB-based repression." (PMID 33530304, 2021). "Specifically, viral 3Cpro colocalized with PML NBs and induced PML-III degradation during final stages of infection." (PMID 33807177, 2021). "During infection with HIV-1, a lentivirus belonging to the family Retroviridae, PML NBs rapidly relocalize from nuclear to cytoplasmic aggregates." (PMID 34513832, 2021). "U2OS PML+/+ and PML-/- cell lines were infected with HHV-6B and integration frequencies were assessed four weeks post infection by droplet digital PCR." (PMID 32658923, 2020). "Binding to PML and disruption of PML bodies have been considered pivotal to IE1 function and hCMV replication, at least upon low MOI infection." (PMID 32365141, 2020). "During infection with E2A SCM virus with reduced E2A SUMOylation, the localization of PML tracks was displaced from the HAdV RCs." (PMID 32184235, 2020). "Conversely, expression of IE1dl410-420 led to a marked increase in infection-related induction of the IFNB1, IFNL1, CCL5, TNF and PML genes." (PMID 32365141, 2020). "During HSV-1 ΔICP0 mutant infection, recruitment of these DDR proteins occurs in close proximity to vDNA in a PML and Sp100 independent manner." (PMID 32416261, 2020). "ICP0 mediates the degradation and dispersal of host factors, including PML and IFI16, away from infecting viral genomes to disable intrinsic and innate immune defences activated in response to infection." (PMID 30901352, 2019). "As nuclear infection in and of itself was not sufficient to induce the stable recruitment of HIRA to vDNA or PML-NBs by 180 mpi, we next evaluated HIRA localization at PML-NBs under infection conditions that enabled the induction of innate immune defences." (PMID 30901352, 2019). "During the initial stages of infection, ICP0 localizes to PML-NBs prior to mediating their disruption." (PMID 31781083, 2019). "This leads to increased cell survival by the silencing of PML proteins, and EBNA1 thereby protects virion production from apoptosis and promotes lytic infection." (PMID 30133498, 2018). "We used herpes simplex virus with bioorthogonally labeled genomes to detect host factors recruited to viral DNA shortly after its nuclear entry and found that the cellular IFI16, PML, and ATRX proteins colocalized with viral DNA by 15 min post infection." (PMID 30465651, 2018). "Alternatively, HIV pre-integration complexes induce nuclear PML shuttling to cytoplasm, in which PML sequesters the HIV genome and blocks the viral transduction in the early infection stage." (PMID 29416846, 2018). "Infection of fibroblasts with HVS results in restriction of immediate-early gene expression, which can be alleviated by siRNA mediated knock down of PML; PML is thus also a restriction factor for HVS infection." (PMID 29065450, 2017). "The addition of IFN-β very strongly inhibited (>20-fold) the infection of THP-1 cells, and the low numbers of infected cells prevented a fine analysis of the role of PML in this inhibition." (PMID 28656178, 2017). "After infection of primary cells with HSV or CMV, or transient transfection with naked plasmid DNA, HIRA re-localizes to PML bodies, sites of cellular anti-viral activity." (PMID 28981850, 2017). "During infection with ICP0-null mutant HSV-1, PIAS4 SIM-mediated direct or indirect interactions with PML predominate, suggesting that infection enhances PIAS4 SIM-mediated interactions over those mediated by its other domains." (PMID 26937035, 2016). "We used quantitative PCR (qPCR) to investigate the effects of PML on HIV-1 DNA synthesis and nuclear import, two early infection steps frequently affected by previously discovered restriction factors." (PMID 27000403, 2016).